IL1B (interleukin 1 beta)
Diseases named in the same sentence as IL1B in open-access papers (continued):
Sharing a sentence is not in itself a finding about the gene and the disease.
colitis (continued). "Our results showed that IL-1β, IL-6, and IL-17A were all down-regulated in mice with DSS-induced colitis, following treatment with M2b macrophage exosomes." (PMID 31749791, 2019). "The levels of TNFα, IL-1β, and IL-6 in colon tissues of WT mice remained high at d 6 post DSS challenge, correlated with severe tissue damage and worse colitis outcome as observed above." (PMID 31555304, 2019). "TGP were also shown to attenuate TNBS-induced colitis in rats by decreasing up-regulated pro-inflammatory cytokines TNF-α and IL-1β, and increasing down-regulated anti-inflammatory cytokine IL-10." (PMID 31461974, 2019). "IEC-specific VDR KO mice display worse colitis and higher expression of TNF-α, IL-1β, and MCP-1 than wild-type mice." (PMID 30804707, 2019). "We found that TOE attenuated the clinical symptoms, lowered the inflammatory scoring and inhibited the secretion of proinflammatory factors TNF‐α, IL‐1β and IL‐6 in DSS‐induced colitis." (PMID 31565850, 2019). "Treatment of UC with SP, honey, and combination regimen significantly reduced TNF-α, IL-1β, IL-6, MDA, MPO, NO, and PGE2, and increased TAC, GSH, GPx, and SOD in interventional groups compared to the AA-colitis group (P<0.05)." (PMID 34466462, 2019). "To gain insight into the effect of MMI-0100 on the DSS-induced colitis, we assessed a series of pro-inflammatory cytokines at mRNA levels, such as TNF-α, IL-6, IL-1β, TGF-β, IFN-γ, IL-17A, COX-2 and iNOS." (PMID 31382637, 2019). "Administration of MSCs-EVs down-regulated expression of NF-κB p65 and reduced production of NO, IL-1β and IL-18 in colon macrophages, resulting in alleviated 2,4,6-trinitrobenzene sulfonic acid (TNBS)-induced colitis." (PMID 31835680, 2019). "To find out if IL-1 was responsible for colitis development in B6DC-LMP1/CD40-mice, we next blocked IL-1β by injection of a specific blocking antibody." (PMID 30653608, 2019). "With respect to the cytokine levels of the colon tissue, the level of the IL-1β proinflammatory cytokine was significantly lower in the TMSC, TMSC-CM, and TMSC-CM-conc groups than in the colitis control group (p = 0.0188, ANOVA)." (PMID 31790467, 2019). "In rats with colitis rats treated with SSW, expression of IFN-γ, IL-1β, and IL-17 was suppressed, and expression of IL-4 was increased." (PMID 30894816, 2019). "We have previously shown the anti-inflammatory effect of physical exercise; recreation led to reduced area of lesions and decreased expression of Il-1β (interleukin 1 beta), CXCL1 (C-X-C motif chemokine ligand 1), and MPO in a rat model of colitis." (PMID 31010141, 2019). "Significantly lower concentrations of inflammatory cytokines of innate immunity (p < 0.05 for IL-1β, TNF-α, and IL-6) were observed in serum samples of DSS-treated Gal-3−/− mice at the end of induction phase of colitis." (PMID 31336879, 2019). "In the experimental colitis model, activated DCs produce numerous pro-inflammatory cytokines including TNF-α, IL-1β, IL-6, and IL-12 and express high levels of co-stimulatory molecules including CD80 and CD86." (PMID 31286993, 2019). "It confirms that CRHR2 receptor antagonists (Astressin2B) can block the TLR4/NF-κB signaling pathway in DSS-induced colitis mice to reduce the levels of TNF-α, IL-6, and IL-1β in serum, thereby protecting the colon mucosa." (PMID 30881446, 2019). "Consistent with increased access of these pro‐inflammatory factors, serum levels of IL‐1β, TNF‐α and IL‐6 were elevated in DSS‐treated mice, which were drastically reduced in mice colitis model following CHC treatment." (PMID 31418947, 2019). "Oral administration of AL-1 significantly attenuates the production of IL-1β, IL-6, TNF-α, PGE2, and IFN-γ in the sera of colitis mice." (PMID 31687082, 2019). "In a colitis rat model, the number of ulcers, pathological scale, and TNF-α, IL-1β, and IL-6 levels were reduced following treatment with KJL." (PMID 31534467, 2019).
colitis (continued). "A study administrated with aspirin-triggered RvD1 (AT-RvD1) and RvD2 reported a reduced generation of IL-1β, CXCL1, NF-κB, VCAM-1, and ICAM-1 in DSS- and TNBS-induced colitis." (PMID 31780872, 2019). "In summary, our findings show that M2b macrophage exosomes attenuate disease activity, up-regulate Treg cells and IL-4, and reduce pro-inflammatory cytokine (IL-1β, IL-6, and IL-17A) production in mice with DSS-induced colitis." (PMID 31749791, 2019). "Increases in the level of TNF-α, IL-6 and IL-1β during IBD and experimental colitis have been well documented." (PMID 30024891, 2018). "Given our findings that HF inhibits IL-1β, we therefore investigated the therapeutic potential of HF in a murine model of DSS-induced colitis." (PMID 29621237, 2018). "We also noted that colonic levels of pro-inflammatory cytokines, such as INF-γ, IL6, IL1-β, TNF-α, and IL10, were significantly (P < 0.001) increased in mice with DSS-induced colitis, as compared to healthy mice." (PMID 28528363, 2018). "Our data indicate that HF significantly reduces serum IL-1β levels and the inflammatory pathology in a murine model of DSS-induced colitis and highlight the therapeutic potential of HF-induced GCN2–AAR pathways in controlling intestinal inflammation." (PMID 29621237, 2018). "In consistence with these results, COMMD10-deficiency in Ly6Chi monocytes, but not in intestinal-resident lamina propria macrophages, led to increased IL-1β production and aggravated colonic inflammation in a model of DSS-induced colitis." (PMID 30487795, 2018). "In a murine model of DSS-induced colitis, an increase in mRNA and protein expression in intestinal epithelial cells for TLR4 that was correlated with IL-1β expression was demonstrated." (PMID 30138385, 2018). "DCA enema significantly aggravated DSS-induced colitis in mice and S1PR2 inhibitor as well as inflammasome inhibition by cathepsin B antagonist substantially reducing the mature IL-1β production and alleviated colonic inflammation superimposed by DCA." (PMID 29854830, 2018). "In this study, a significant increase (10-fold) in gene expression of IL-1β was observed in DSS treated mice (p < 0.01), suggesting that DSS-induced colitis involves the IL-1 signaling family." (PMID 29890681, 2018). "The combination drug modulated the production of both proinflammatory cytokines (IL-6, IL-1β, and IL-17) and an anti-inflammatory cytokine (IL-10) in mice with DSS-induced colitis." (PMID 29466999, 2018). "Colitis in IL10 KO mice is attributed to the increased production of inflammatory mediators such as TNF and IL1b as well as to a hyper-activated Th1 response." (PMID 29985419, 2018). "Moreover, wt mice co-housed with Il-18 but not with Il-1β or I1-1R deficient mice had an increased susceptibility to DSS-induced colitis suggesting that the colonic defect in Il-18 is the major downstream event responsible of enhanced colitogenic microbiota in Nrp6−/− mice." (PMID 29868004, 2018). "Our in vitro results on LPMCs show complete inhibition of IL-1β by 1 μM of MCC950, which explains how MCC950 attenuated colonic inflammation in our in vitro spontaneous colitis model Winnie." (PMID 29872077, 2018). "We found that metformin ameliorated the induction of colitis and reduced the levels of pro‐inflammatory cytokines IL‐6, TNF‐a and IL‐1β." (PMID 29148173, 2018). "Our present study showed that the induction of colitis by DSS led to damage and inflammatory infiltration of the colonic mucosa and increased the mucosal concentration of TNF-α, IL-1β and IL-6." (PMID 29495327, 2018). "In DSS-induced colitis, the roles of TNF-α and IL-1β differ in origin and function; TNF-α is more specific to colon epithelial cells, and IL-1β is more specific to myeloid cells." (PMID 29959357, 2018). "Next, we observed that the expressions of NLRP3, IL-1β, and ASC proteins in colonic tissue were increased, which suggested that the NLRP3 inflammasome pathway was activated in the pathogenesis of colitis in mice." (PMID 29507526, 2018).
colitis (continued). "Genetic studies have shown that inflammatory cytokines, such as TNFα, IL-1β, IL-6, and IFN-γ, are elevated in colitis, and are important in the development of mucosal inflammation." (PMID 29467753, 2018). "The mRNA expressions of IL-1β, IL-6 and TNF-α in the colons of colitis mice significantly increased, and bergenin (20, 50 mg/kg) and 5-ASA (100 mg/kg) showed obvious inhibition." (PMID 29375382, 2017). "We found an elevated protein expression of inflammatory cytokines including IL-6, IL-23, IL-1β, and TNF-α in the mucosa of colitis mice compared to the control group." (PMID 29375374, 2017). "To investigate the mechanism of Huaier-mediated protection from murine colitis, we tested the expression of NLRP3 and IL-1β in colon samples by immunohistochemistry." (PMID 28380426, 2017). "Significantly higher levels of mRNAs of pro-inflammatory cytokines, IL-1β, IL-6, IL-17 and TNF-α, were found as early as day 6 in our colitis model than control group, showing ~5.7, ~6.7, ~12.0 and ~3.2 fold increase, respectively." (PMID 28854223, 2017). "In line with the morphological appearance of colitis in the knockout mice, the expression of proinflammatory cytokines and chemokines, including IL6, IL1β, Cxcl1, and Ccl2, are dramatically increased in the colonic epithelial cells of the knockout mice." (PMID 28296893, 2017). "The data in this paper revealed that the expression levels of IL-17, IL-21, IL-23, IL-6, IL-1β, TNFα, and IL-12 in mLN tissues significantly decreased in CD169-DTR colitis mice compared to those in WT colitis mice." (PMID 28694804, 2017). "The expressions of ICAM-1, IL-1β, IL-16, CXCL10, MCP-1, CXCL9, CXCL12, and TIMP-1 were greatly reduced in MSC-EX-treated colitis group compared with those in the PBS-treated colitis group." (PMID 28842625, 2017). "Tumour necrosis factor alpha (TNF-α), Interleukin 6 (IL-6), Interleukin 1 beta (IL-1β), and cyclooxygenase-2 (COX-2) play a pivotal role in the onset of colitis." (PMID 28415628, 2017). "In our study, TER successfully alleviated acute colitis by suppressing the high-production of TNF-α, IL-1β, and IL-12 in colon explants." (PMID 28553294, 2017). "Increased serum and tissue levels of pro-inflammatory cytokines such as IL-6, IL-1β and TNF-α are characteristic features of colitis and many other chronic inflammatory diseases." (PMID 28634361, 2017). "IL-1β and IL-6 are crucial in IBD and arrest DSS-induced colitis by inhibiting the pro-inflammatory activity and possible downstream proangiogenic activity." (PMID 28556814, 2017). "In line with the results obtained in patients with CD, prolonged hypoxia downregulated NF-κB signaling and the expression of Tnfα, Il-6, and Il-1β in the DSS and Il-10−/−mouse models of colitis." (PMID 28740109, 2017). "In IBD, several inflammatory cytokines, such as interleukin-1β (IL-1β), interleukin 6 (IL-6) and TNF-α, mediate the progression of colitis and CAC18–20." (PMID 28701727, 2017). "Data from animal models indicate that OLE attenuates the inflammatory process in DSS-induced colitis by downregulating the expression of COX-2 and pro-inflammatory cytokines, such as TNF-alpha, IL-1β, IL-6 and IL-17." (PMID 28420140, 2017). "In contrast, the intestinal macrophages of p85α+/− colitis mice expressed similar levels of TNF-α, IL-1β, IL-6 and iNOS mRNA compared with intestinal macrophages of p85α+/− normal mice." (PMID 28733636, 2017). "We found that oral administration of DSS in NLRP3−/− mice induced a less severe colitis than WT mice and produced lower levels of MPO and IL-1β in colonic tissues, which suggested the important role of NLRP3 inflammasome in DSS-induced colitis." (PMID 28553294, 2017). "The administration of HQD, however, significantly suppressed the accumulation of TNF-α, IL-6, IL-1β, and COX-2 in the colon tissues of mice with DSS-induced colitis." (PMID 28415628, 2017).
colitis (continued). "The intestinal macrophages of WT colitis mice expressed high levels of TNF-α, IL-1β, IL-6 and iNOS mRNA compared with the intestinal macrophages of WT normal mice." (PMID 28733636, 2017). "In colon tissues of PBS-treated mice with colitis, the mRNA expression levels of TNF-α, IL-1β, IFN-γ, and IL-17 were considerably increased, whereas that of IL-10 was only slightly increased." (PMID 28701721, 2017). "Dietary supplementation with genistein inhibited the overexpression of IL-1β and IFN-γ, suggesting an anti-inflammatory functions in DSS-induced colonic inflammation." (PMID 28977871, 2017). "Previous studies have described that the DSS-induced colitis model induced high amounts of Th1 cytokines (TNF-α, IL-1β, IL-6)." (PMID 27965594, 2016). "Compared with the control, the serum levels of IL-1β, IL-6, IL-10, IFNγ, and TNFα were increased in DSS colitis mice." (PMID 27177331, 2016). "The present study in vivo found that sodium propionate inhibited the up-regulation of proinflammatory factors IL-6, IL-1β, and TNF-α mRNA level in the colon of colitis mice." (PMID 27574508, 2016). "To better understand the mechanism by which AMT-E ameliorates the DSS-induced colitis, we assessed the colonic production of the inflammatory cytokines TNF-α and IL-1β and the anti-inflammatory cytokine IL-10." (PMID 27527191, 2016). "The murine DSS-induced colitis model exhibits a distinct cytokine profile with elevated levels of TNF-α, IFN-γ, IL-1β, IL-6, and IL-12." (PMID 27293323, 2016). "LL202 inhibited the high-production of IL-1β, IL-6 and TNF-α dramatically both in the colon and serum of DSS-induced colitis mice." (PMID 27590510, 2016). "Administration of rifaximin after induction of colitis has decreased the activity of MPO and reduced concentration of IL-1β and TNF-α in colonic mucosa, reflecting the reduction in the local inflammatory reaction." (PMID 27433160, 2016). "To examine the effects of MALT1 inhibitors on the cytokine expression in acute DSS colitis model, we measured the levels of IL-1β, IL-6, TNF, IFN-γ, IL-17A and IL-18 in colons of mice following induction of colitis and treatments with MALT1 inhibitors." (PMID 27105502, 2016). "In our study, the levels of TNF-α, IFN-γ, and IL-1β were remarkably reduced by AaEE in DSS-induced colitis mice, suggesting that the protective effect of AaEE against colonic injury is related to the downregulation of TNF-α, IFN-γ, and IL-1β." (PMID 27635116, 2016). "Of note, the dynamics strikingly differed between IL-1β and IL-18 during the development of OXA-induced colitis, whereas exogenous administration of either cytokine had a protective effect against the colitis." (PMID 27966619, 2016). "The IL-1β, -6, -8, -17 and TNF-α protein levels were downregulated significantly in DSS induced colitis mice treated with Grim19 compared with control mice." (PMID 27258062, 2016). "Although we found that both IL-1β and IL-18 played a protective role in OXA-induced colitis, the roles of these cytokines on colonic inflammation are inconclusive and controversial." (PMID 27966619, 2016). "Real time RT-PCR quantitation confirmed that pro-inflammatory cytokines and chemokines (CCL2, IL-1β, IL-6, IL-23, TNF-α, IL-17A and IL-17F) were elevated in quiescent and active colitis biopsies." (PMID 27271344, 2016). "Previous studies have demonstrated that ITGA4 is hypermethylated in inflamed colon tissue/colitis, and that the treatment of anti-ITGA4 antibodies further aggravate colitis by IL-1β, TNF-α, and IFN-γ recruitment." (PMID 27111221, 2016). "Pro-inflammatory cytokines (TNF-α, IL-1β, and IL-6) levels and MPO activity from colitis rat colon tissue were significantly increased compared to those in sham group." (PMID 27303297, 2016). "Our data also showed high levels of IL-1β, IL-6 and TNF-α in homogenates of colonic segment from mice with TNBS-induced colitis." (PMID 25853847, 2015).
colitis (continued). "We conclude that HFD delays the healing of colitis in trained rats via decrease in CBF and plasma IL-1β, TNF-α, TWEAK, and leptin levels and the release of protective irisin." (PMID 25684862, 2015). "Finally, in rats with chemically-induced colitis, treatment with G ameliorated symptoms of colitis, while decreasing both systemic and colonic inflammation, as measured by serum concentrations of IL-8 and amyloid P component, and colonic expression of NF-kB, IL-1β, and TNFα, respectively." (PMID 25719429, 2015). "Experimental colitis was quantified in the rat model, macroscopically and by measuring the activity of tissue MPO and iNOS and levels of TNFα and IL-1β." (PMID 25949237, 2015). "The administration of CBS effectively reduced the mRNA expression of TNF-α, IL-1β, and IL-6 in the colon tissue of mice with DSS-induced colitis." (PMID 26579201, 2015). "The development of experimental colitis in HFD rats was accompanied by the fall in CBF, the increased expression of proinflammatory cytokines IL-1β, TNF-α, and TWEAK, and decreased release of protective adipokines (e.g., adiponectin)." (PMID 25684862, 2015). "Treatment with HBO normalized IL-1β, TNF-α, CINC-1 and IL-10 (P < 0.05) in rats subjected to colitis by TNBS." (PMID 25926972, 2015). "IL-1β, IL-6 and TGF-β, which had high levels in colitis, were significantly decreased in the MSC treated group." (PMID 25889203, 2015). "We found a significant increase in the levels of IL-1β, IL-6, IL-17, TNF-α and IFN-γ in the plasma of mice with colitis." (PMID 25625560, 2015). "In accordance with our data, it was earlier shown that the retinoic acid, which has an immunomodulatory effect, ameliorates the TBNS colitis via inhibition of TNF-α, IL-6, IL-1β secretion and MPO activity in mice." (PMID 25853847, 2015). "Administration of L. plantarum and L. brevis reduced IL1β, TNFα, and IFNγ, as well as the protein expressions of IL1β and IL6, and the signs of colitis in DSS-induced colitic mice." (PMID 26347738, 2015). "Curcumin has been shown to attenuate colitis in the dinitrobenzenesulfonic acid (DNB)-induced murine model of colitis with a reduction in MPO activity, IL-1β expression, and reduction of p38 MAPK." (PMID 26007179, 2015). "There was a significant increase in the levels of IL-1β, IL-6, IL-17, TNF-α and INF-γ in the plasma of the mice with colitis." (PMID 25625560, 2015). "In patients with IBD, the production of the inflammatory cytokines TNF-α, IFN-γ, IL-6, IL-1β, IL-10 and IL-12 are in agreement with the results of the TNBS model of colitis." (PMID 26561804, 2015). "Plasma levels of proinflammatory cytokines IL-1β, TWEAK, and TNF-α were significantly elevated in animals with TNBS-induced colitis (P < 0.02) in comparison with intact rats." (PMID 25684862, 2015). "Increased expression of cytokines, such as IL-1β, IL-6, TNF-α, and interferon-γ (IFN-γ), is observed after TNBS treatment, suggesting that cytokines are involved in the pathogenesis of TNBS-induced colitis." (PMID 24995035, 2014). "IL1β expression levels increased in all treatment groups; however, this was only statistically significant in WTWTBM mice following DSS-induced colitis." (PMID 25460165, 2014). "Pro-inflammatory cytokines such as TNFα, IL1β, and IL6 play pivotal roles in the pathogenesis of colitis." (PMID 25072851, 2014). "When treated with p38 inhibitor, mucosal IL-1β and TNF-α levels were reduced in DSS colitis model consistent with what we found for E.faecalis treatment." (PMID 24830946, 2014). "The administration of polyphenols significantly suppressed the DAI score, along with reducing the histological severity of colitis and downregulating the expression of pro-inflammatory signaling factors, such as TNF-α, IL-1β and IL-6." (PMID 25409433, 2014). "Recently we demonstrated that brain stimulation of the CAP alleviates the disease severity and suppresses colonic proinflammatory cytokine (IL-6, IL-1β and TNF-α) levels in experimental DSS-induced colitis." (PMID 25295619, 2014).